CCL2 (C-C motif chemokine ligand 2)
Diseases named in the same sentence as CCL2 in open-access papers (continued):
Sharing a sentence is not in itself a finding about the gene and the disease.
infection (continued). "Chemokines C–C motif chemokine ligand 2 (CCL2), also known as monocyte chemotactic protein 1 (MCP-1), which can recruit monocytes to reach inflammation, infection, trauma, ischemia and other sites." (PMID 33228784, 2020). "We found that ex vivo infection of whole blood with MVA significantly induced the production of IL-8, CCL2, and CCL4 in monocytes and HLA-DRhigh DCs of HIV-ART patients and healthy persons." (PMID 33013882, 2020). "The analysis in this study revealed an increased inflammatory response, and the expression of CXCL1, CXCL12, CCL2 and CCL5 was significantly increased upon natural street RABV strain infection of dogs or humans compared to artificial mouse infection." (PMID 33081802, 2020). "In general, H3N2 and H5N1 infection induced IFN-α, TNF-α, MCP-1 (CCL-2), IL-1β, and IL-6 responses in ANP32B+/+ mice were reduced in ANP32B−/− mice, particularly 3 days post infection." (PMID 32231671, 2020). "Reportedly, chemokines are specialized in the recruitment of various cells, including neutrophils (IL-8), monocytes (CCL2), Th1 cells (CXCL9, CXCL10), Th2 cells (CCL17, CCL21), and Th17 cells (CCL20), to sites of infection." (PMID 32231137, 2020). "The TLR3 signal also causes an upregulation of TLR2, which participates in the expression of IL1β, IL6, CCL2, and CCL5 genes by primary C57BL/6 astrocytes following a TMEV-BeAn infection." (PMID 30669615, 2019). "On the same day of challenge with the Y strain infection, A/Sn mice were treated with the anti-CXCR3 or anti-CCL2 monoclonal antibodies." (PMID 31356587, 2019). "Nonetheless, PKR is important for the production of IFN-I, IL6, CCL2, and CXCL10 in primary SJL astrocyte cultures, whereas TLR3 plays only a minor role in the responses to a TMEV-BeAn infection." (PMID 30669615, 2019). "Monocytes sense Tg-infection through Alarmin S100A11 secreted from infected cells, which results in production of the chemokine (C-C motif) ligand 2 (CCL2)." (PMID 31830133, 2019). "Our previous studies showed that Leptospira induces changes in the levels of chemokines in organs of mice in the first hours after infection, including CCL2/MCP-1." (PMID 30616505, 2019). "Although the kinetics of mRNA induction by P. gingivalis differed between individual genes, I-BET151 uniformly reduced IL8, IL1B, CCL2, and CCL5 expression at 4 and 24 h post-infection." (PMID 31114581, 2019). "While IL-1α and IL-1β levels in WT and IL-1R−/− mice were similar, levels of IL-6, IL-12p70, IFN–γ, CCL2, CCL3, and CXCL9 were significantly lower in IL-1R−/− mice compared with wild-type mice following infection with P1/7 (p < 0.05)." (PMID 31262357, 2019). "This process ensues the development of a cytokine cascade, some of them with protective roles, including IL-12, IL-13, IL-6, CXLL2, CCL7, CCL2, TNF-α, and consequent neutrophils recall in the site of infection." (PMID 31508399, 2019). "To study the influence of B1R/B2R on the inflammatory response at the primary site of infection, we measured cytokine (tumor necrosis factor (TNF) α, interleukin (IL)-1β, and IL-6) and chemokine (CXCL1, CXCL2, and CCL2) levels in whole lung homogenates." (PMID 30874974, 2019). "The protein levels of CCL2, CCL3, CCL4, and CCL5 in the liver of μMT mice 6 weeks after infection were significantly increased compared with those of WT mice." (PMID 31194740, 2019). "The findings of a significant reduction of CCL2 and IL-6 in Myd88−/− mice in response to NMII infection are consistent with the observed reduction in leukocyte infiltration and granuloma response." (PMID 30800124, 2019). "Compared to mock infection, RSV infection via both inoculation methods resulted in increased BAL concentrations of CCL2 (MCP-1), CCL5 (RANTES), CXCL1, CXCL10 (IP10), IFN-α, IFN-γ, and TNF." (PMID 31163619, 2019).
infection (continued). "In our study, BVDV-2 infected goat PBMCs showed increased transcription of CCL3, CCL4, CCL5, CCL20, CXCL10 and decrease of CCL2, suggesting that such chemokines may contribute to the recruitment and regulation of macrophages or other inflammatory cells to the infected sites after infection." (PMID 31226933, 2019). "A single unilateral injection of EcoHIV (1 × 106 pg) directly into the caudate putamen resulted in a significant increase in inflammatory markers (TNFα, IL-1β, IFNγ, CCL2, CCL3, CXCL10) 5 days after infection." (PMID 31263138, 2019). "Herein, a single unilateral injection of EcoHIV (1 × 106 pg) directly into the caudate putamen resulted in a significant increase in inflammatory markers TNFα, IL-1β, IFNγ, CCL2, CCL3 and CXCL10 5 days after infection." (PMID 31263138, 2019). "The chemokine CCL2 is a ligand of the chemokine receptor CCR2, which plays a major role in mobilization of inflammatory monocytes in response to infection." (PMID 30169526, 2018). "At T1, 2 months post-infection, the LM17- and LJL143-immunized dogs presented higher levels of IFN-γ, IL-6, IL-18, CXCL10, GM-CSF, IL-7, IL-15, and CCL2 in comparison to controls." (PMID 30519235, 2018). "At 4 months after infection (T2), the dogs immunized with either salivary protein presented higher levels of IFN-γ, IL-6, IL-18, GM-CSF, IL-7, IL-15, TNF, and CCL2 when compared to controls." (PMID 30519235, 2018). "The LJM17-immunized dogs presented a prolonged pattern of pro-inflammatory response that persisted until 4 months after infection, with the exception of IL-2, CXCL10, IL-8, and CCL2." (PMID 30519235, 2018). "LTB4/BLT1 axis is required for the synthesis of chemokines that recruits neutrophils (CXCL1 and CXCL2), monocytes (CCL2, CCL8, and CCL7) and T cells (CCL4) at both days 1 and 9 after infection." (PMID 30102746, 2018). "Subjects with Staph, Cor/All, Mor, and Ps/Mix clusters were found to have differences in CCL2, CCL20, IL-6, and G-CSF responses during the infection." (PMID 30061588, 2018). "The concentrations of MCP-1 (CCL2), IL-10, and IL-12p70 in the serum from both B6 C5+/+ and B6 C5+/+ mice were below detectable levels on the third and the sixth days post-infection." (PMID 29568732, 2018). "After infection of μBS by ZIKV-BR and ZIKV-UG, upregulation of TNF-α, IL6, IL1b, and CCL2 was observed when compared with BS." (PMID 30619100, 2018). "Several chemotactic proteins have been confirmed to be implicated in the recruitment of macrophages to sites of inflammation and infection, including CCL2, which is also known as monocyte inflammatory protein 1 (MCP-1)." (PMID 30619312, 2018). "Further, in this model and others, increased levels of IP-10 (CXCL10), MCP-1 (CCL2), and IL-6 have been observed, which have been characterized as hallmarks of H5N1 human infection." (PMID 30568659, 2018). "CCL2, also known as monocyte chemoattractant protein-1 (MCP-1), recruits monocytes to sites of inflammation, infection, and injury." (PMID 29945607, 2018). "Infection leads to Toll-like receptor (TLR) activation, production of inflammatory cytokines such as IL-6, IL-1β, TNF-α, CCL2, IFN-γ, and IL-17, and neutrophil and macrophage recruitment." (PMID 30487793, 2018). "CCL2, CCL3, and CCL5 belonging to inflammatory chemokines, are produced in high concentrations during infection or injury and determine the migration of inflammatory leukocytes into the damaged area." (PMID 30480097, 2018). "Levels of type I IFNs, TNF-α, IL-6 and CXCL1 as well as CCL2, and IFN-γ were all significantly higher in lungs of 6:2 Tky/05 virus infected mice than in the other three groups at day 2 post infection." (PMID 29300777, 2018). "Pre-colonization by NPI followed by CP1-infection showed increased VEGF and IL4 expression when compared to CP1-alone (analysis 3) and decreased levels of CCL2/3 and 4, and IL17." (PMID 30479364, 2018).
infection (continued). "IFN-alpha (IFN-α) was detected in the lungs of 6:2 Tky/05 virus-infected mice along with IL-6 at day 2, whereas levels of TNF-α, CXCL1, CCL2 and IFN-γ continued to rise through day 3 post infection." (PMID 29300777, 2018). "It seems that expression of these chemokines, at least with regard to CCL2/MCP-1, is highest in the early phase of cell infection and is dependent on the pp71 viral protein." (PMID 29467963, 2018). "At day 6 post-infection, C57BL/6J mice also exhibited higher levels of IL1A, IL1B, CCL2, CCL3, IL2, IL10, and IL6." (PMID 30713529, 2018). "In the liver on day 7 post-infection, the expression of iNOS, IL-1β, IL-6, IL-12 p40, TNF-α, IL-10, TGF-β, CCR2, CCL2, IFN-γ and IL-4 was significantly up-regulated, and the expression of Arg-1 was down-regulated in both of MRP14-KO mice and WT mice." (PMID 29902248, 2018). "Chemokines, granule proteins, and other molecules released by neutrophils (e.g., CCL2, CCL3, CCL19, CCL20, S100A8, and S100A9) recruit monocytes to the site of infection." (PMID 28626346, 2017). "In contrast, the secretion of monocyte-recruiting chemokine (MCP-1/CCL2) by cells from mice infected with strain M299 was lower than those infected with strain H37Rv, at least at the acute stage of infection." (PMID 28306733, 2017). "In isolated primary mouse ATII, infection with lentivirus coding for specific shRNA FXYD5 prevented the LPS-stimulated increase in FXYD5 and CCL2 mRNA by 62 and 30%, respectively." (PMID 28620381, 2017). "In the current study, we demonstrate that inflammatory monocyte infiltration into the brain during acute TMEV infection requires CCR2 and that neurons are a key source of CCL2 driving this trafficking during the earliest stages of infection." (PMID 29202854, 2017). "After aerosol Mtb challenge, Card−/− mice succumbed early to the infection with higher Mtb burden, accelerated granulocyte (MPO-expressing cell) recruitment, and higher abundance of the proinflammatory factors CCL2, CXCL1, and G-CSF." (PMID 28626346, 2017). "Optimal expression of Ccl2, Ccl3, Ccl4, and Cxcl1 depends on DDR signaling in macrophages, and these chemokines regulate the migration of innate immune cells during infection." (PMID 28362262, 2017). "In conclusion, we have demonstrated that a basal to apical migration of CD172a+ cells in nasal mucosa was present during infections with neurological EHV-1 strains, with CCL2 and CCL5 involved in the attraction of CD172a+ cells towards the infected regions." (PMID 28241864, 2017). "In response to infection with hRSV, human AEC-derived cell lines secrete cytokines and chemokines in vitro, including IL-6, IL-8, CCL2, CCL3, and CCL5 that promote the recruitment of monocytes and eosinophils to the site of infection." (PMID 29230219, 2017). "Campbell and Spector identified that when resting CD4+ T cells were exposed to CCL2, upregulation of CXCR4 expression occurred, and the elevated CXCR4 expression increased infection by CXCR4-tropic HIV." (PMID 29085362, 2017). "We next measured pro-inflammatory mediators in splenic tissue by ELISA and observed significant increases in IL-6, CXCL1(KC), IFN-γ, TNF-α, CCL2 (MCP-1), and MMP-3 levels after infection." (PMID 28874800, 2017). "LysM-GFP monocyte-neutrophil reporter mice received 20 μg goat anti-CCL2 IgG, 20 μg goat anti-CCL7, or 20 μg goat IgG by intraperitoneal injection at − 12, 0, and + 12 h relative to time of infection." (PMID 29202854, 2017). "CCL2, also known as monocyte chemoattractant protein-1, is involved in chemotaxis of CCR2-expressing memory T cells, monocytes, and DCs to sites of inflammation produced by either tissue injury or infection." (PMID 28261205, 2017). "PGL activated the STING cytosolic sensing pathway in resident macrophages, inducing the production of the chemokine CCL2, which in turn recruited circulating CCR2+ monocytes toward infection." (PMID 28844797, 2017).
infection (continued). "CCL2 is a chemoattractant for CD4+ T cells, monocytes/macrophages, and NK cells, recruiting them to the sites of infection and inflammation." (PMID 29085362, 2017). "After infection, NK1.1+ cell depleted-mice exhibited significantly reduced levels of the cytokines IL-6, IL-12p40, and G-CSF, and of the chemokines CCL2 and CCL5 compared to mock-treated infected mice (P < 0.05)." (PMID 28706510, 2017). "During an infection with another alphaherpesvirus, HSV-1, in mice, it has been reported that CCL3 attracts NK cells, CCL2 recruits monocytes, and CCL5 recruits monocytes, NK cells, and PMNs while CXCL9 recruits T-cells to the sites of infection." (PMID 28241864, 2017). "Seven days post infection, CS + IAV mice had increased mRNA expression of pro-inflammatory chemokines (CCL-2, CXCL-2, CXCL-9, CXCL-10), cytokines (GM-CSF, TNF-α, IL-1β, IL-6) and proteases (MMP-12) compared to sham + IAV + diluent mice or CS + diluent mice." (PMID 26877172, 2016). "Besides chemokines, cytokines such as TNF-α are released acutely in response to injury or infection, and function to initiate and maintain the inflammatory process in part by stimulating other pro-inflammatory cytokines (e.g., IL-1α, IL-1β, and IL-6) and chemokines (e.g., CCL2, CCL3, and CXCL2)." (PMID 26860080, 2016). "Seven days post infection, CS + IAV mice had increased mRNA expression of pro-inflammatory chemokines (CCL-2, CXCL-2), cytokines (GM-CSF, TNF-α, IL-1β, IL-6) and proteases (MMP-12) compared to sham + IAV + diluent mice." (PMID 26877172, 2016). "The same pattern was observed for CXCL10 (age: p<0.001, infection: p=0.609, infection*time: p =0.684), CXCL1 (age: p<0.001, infection: p=0.865, infection*time: p =0.121), and CCL2 (age: p<0.001, infection: p=0.921, infection*time: p =0.263)." (PMID 26856410, 2016). "Three days post infection, sham + IAV + vehicle mice had increased mRNA expression of pro-inflammatory chemokines (CCL-2, CXCL-2, CXCL-10), cytokines (GM-CSF, TNF-α, IL-1β, IL-6) and proteases (MMP-12) compared to sham + diluent + vehicle mice." (PMID 26877172, 2016). "CCL2 and CCL7 have been shown to regulate cytokine production during infection in the lung and thereby contributing to infection control and host resistance." (PMID 27014275, 2016). "Three days post infection, CS + IAV mice had increased mRNA expression of pro-inflammatory chemokines (CCL-2, CXCL-2), cytokines (GM-CSF, TNF-α, IL-1β, IL-6) and proteases (MMP-12) compared to sham + IAV + diluent mice." (PMID 26877172, 2016). "Processes related to cytoskeletal remodeling and cellular junctions, as well as inflammatory responses (IL-2, IL-5, IL-18, CCL2, TNF, IFN, and TGF-β signaling) were also upregulated following infection with C. concisus BAA-1457." (PMID 27677841, 2016). "Infection activates a broad chemokine response to infection, including CXC (CXCL1, CXCL5, CXCL8, CXCL9, and CXCL10) and CC chemokines (CCL2, CCL3, and CCL5)." (PMID 26927188, 2016). "In line with this, the levels of the monocyte-recruiting chemokine CCL2 were much lower in lungs of A20AEC-KO mice than in wild type mice on days eight and twelve after infection." (PMID 26815999, 2016). "CHPV infection of PBMC, Monocytes and B cells strongly stimulated the chemokines (CCL2/MCP-1, CCL5/rantes, CXCL9, CXCL10/IP10) during the course of infection." (PMID 27628855, 2016). "MDM exposed for 20 h to anti-CCL2 or control Ab were challenged with LV/Vpx, and the proportion of GFP+ cells was determined 3 days post-infection by flow cytometry." (PMID 25608886, 2015). "Another network centered on chemokines (CCL2 and CCL4) and IFN-γ also supports a role for cell recruitment and immunity in infection." (PMID 26214306, 2015). "Toward this aim, MDM exposed for 20 h to anti-CCL2 or control Ab were challenged with HIV-1BaL, and total viral DNA was quantified 4 and 7 days post-infection." (PMID 25608886, 2015).
infection (continued). "MDM exposed for 20 h to anti-CCL2 or control Ab were challenged with (VSV-G) HIV-1 and the percentage of p24 Gag+ cells was measured 3 days post-infection." (PMID 25608886, 2015). "Following a 36 hr infection of α and β cells with CVB5, α cells presented higher levels of the viral sensors MDA5 and PKR, of iNOS and CCL2, but lower induction of Viperin." (PMID 26061776, 2015). "After infection, particularly at the 6 h and 8 h time points, CSF2, CCL2, MMP1, and MMP10 proteins were expressed at higher levels in CF than CTRL cells, although the differences were not statistically significant." (PMID 26485688, 2015). "In this context, there is a marked induction of CCL2, CCL3, CCL4, CCL5, CXCL8, and CXCL10 after infection with SIV, as well as a systemic increase of CCL2, CXCL8, and CXCL10 in humans, concurrently with viremia peak after infection with HIV." (PMID 25313360, 2014). "At later stages of infection, RRV-infected OA hOBs showed significantly increased IL-6, IL-1β and CCL2 expression compared to healthy infected controls." (PMID 25407789, 2014). "Microarray analysis revealed that the expression of CCR5, CXCR3 and CCR1 and several of their chemokines including CXCL9, CXCL10, CCL2, CCL3 and CCL9 significantly increases in response to infection in CM-affected mice." (PMID 24476686, 2014). "Further chemokine gene expression studies in brains of ECM-susceptible mice confirmed that CXCL10, CXCL9 and CCL5 and to lesser extent CCL2, CCL7, CCL3, CCL4 and CXCL2 are upregulated during infection with P. berghei ANKA." (PMID 24476686, 2014). "The presence of 33 nm AgNPs at infection led to significantly up-regulated TNF-α, IL-10, CCL2 and down-regulated IL-6 production (p≤0.05), while 46 nm AgNPs significantly down-regulated TNF-α and IL-6 (p≤0.05)." (PMID 25117537, 2014). "In contrast, we observed significantly less production of IL-12p40, IL-12p70, IL-1α, IL-1β, IL-17A, CXCL1, CCL2 and CCL5 in the lungs as the infection progressed." (PMID 25119981, 2014). "Unlike the inducing effect by PGL-mar in the context of zebrafish infection, both PGL-Tb1 and PGL-1 inhibit the CCL2 secretion by macrophages." (PMID 25538905, 2014). "Naïve WT mice show similar expression of CCL2 and CCL20 as compared with naïve IL-4Rα−/− mice, and for both naïve genotypes the levels are considerably lower than upon infection with C. neoformans." (PMID 24475277, 2014). "Similar to CCL2, CXCL10 is a potent attractor of monocytes, macrophages, T-cells, natural killer (NK) cells, and dendritic cells to sites of tissue damage and infection." (PMID 24451065, 2014). "MCP-1, now known as CCL2, is a potent chemokine that contributes to monocyte recruitment during infection or inflammation, and MIF is an important regulator of innate immunity that promotes the proinflammatory functions of immune cells." (PMID 25061613, 2014). "In comparison to HSV-2 infected controls, the presence of 13 nm AgNPs at infection resulted in the significantly up-regulated production of IFN-γ, IL-10 and CCL2 (p≤0.05)." (PMID 25117537, 2014). "At the early stages of infection, NOD2 signaling was shown to activate the CCL2/CCR2 axis that resulted in the recruitment of inflammatory monocytes to the site of infection, which initiated IL-12-mediated bacterial clearance." (PMID 24381573, 2013). "Levels of mRNAs for CCL2, CCL3L1, CCL4, CXCL10, CCR1 and CCR5 were significantly increased in at least one time point following infection in two experiments and CCL5, CCR9 and CXCR4 mRNA were significantly increased in one of the experiments." (PMID 24083897, 2013). "It is important to note that there was very low-level infection of the CD14+CD16+ monocytes, yet there was still exuberant transmigration in response to CCL2." (PMID 23922698, 2013). "Cytokines and chemokines such as CCL2 (MCP-1), CCL3 (MIP1α), CCL5 (RANTES), and CXCL10 (IP10) are responsible for activating leukocytes and attracting them to the lung compartment to clear infection." (PMID 23441208, 2013).